SCD (stearoyl-CoA desaturase)
Diseases named in the same sentence as SCD in open-access papers (continued):
Sharing a sentence is not in itself a finding about the gene and the disease.
Hepatic steatosis (continued). "Cichoric acid plays an important role in reducing hepatic steatosis, as it reduces the expression of lipogenic actors, such as SREBP-1c, DGAT1, FAS, and SCD-1, and also of inflammatory factors such as IL-6, IL-1b, NF-κB, and TNF-α." (PMID 39458995, 2024). "In the liver, DZF intervention resulted in a reduction in hepatic steatosis and lipid droplets, accompanied by a decrease fatty acid synthase (FASN) and stearoyl-CoA desaturase 1 (SCD1) and fatty acid transport protein 2 (FATP2)." (PMID 38327989, 2024). "The transcripts of ACACA, FASN, SCD, FADS2 and FABP1 in chickens with fatty liver were significantly increased compared with those in chickens without fatty liver." (PMID 29642504, 2018). "Substitution of n-6 PUFA with n-3 PUFA (ALA or LC n-3 PUFA) in HFHF diet prevented hepatic steatosis by down regulating the expression of SREBP-1c and SCD-1." (PMID 30026586, 2018). "Elevated serum 16:1 profile is also significantly related to abdominal adiposity and fatty liver disease (FLD), which is a likely reflection of SCD activation and hepatic lipogenesis." (PMID 28870233, 2017). "In our study, TO-treated db/db mice exhibited more extensive hepatic steatosis than the control group, most likely due to SREBP-1c-mediated up-regulation of lipogenetic genes, such as SCD-1 and FAS, etc." (PMID 25909991, 2015). "A previous study confirmed that the suppression of SCD-1 could effectively attenuate HFD-induced insulin resistance and hepatic steatosis." (PMID 35495929, 2022). "Hepatic steatosis might be mediated partly by regulating SREBP-1c, a key transcription factor of lipogenic genes in fatty acid synthesis and TGs, including ACC, SCD, and FAS." (PMID 29295591, 2017). "In a rat model of hepatic steatosis induced by high fructose feeding, PBA intervention significantly lowered TAG content, suppressed lipogenic enzyme acetyl-CoA carboxylase (ACC), fatty acid synthase (FASN) and stearoyl-CoA desaturase (SCD) expression and improved ER stress." (PMID 32824248, 2020). "Therefore, the effect of saury oil on improving hepatic steatosis may possibly be attributed to EPA and may partly be due to inhibition of SCD-1 activity." (PMID 26627187, 2015). "Expression of hepatic genes involved in cholesterol metabolism (SREBP2, HMGCR, and ApoB) and lipogenesis (SREPB1c, SCD-1, FAS, and Acacα) was suppressed in the experimental group, and may have favorably affected hyperlipidemia and hepatic steatosis induced by the high-fat diet." (PMID 22027268, 2011). "In the present study, HFHF feeding induced hepatic steatosis by up regulating the hepatic mRNA expression of SREBP-1c and SCD-1 without altering PPAR-α expression." (PMID 30026586, 2018). "Our results showing downregulations of ADRP on lipid droplets and SCD-1 by nor-NOHA in the liver indicate that arginase inhibition may exert its inhibitory effects on TG formation and development of fatty liver by modulating ADRP and SCD-1 through regulation of PPAR-γ2." (PMID 25057910, 2014).
Insulin resistance (125 papers, 2008 to 2026). Increased resistance towards insulin, that is, diminished effectiveness of insulin in reducing blood glucose levels. "Increased estimated SCD activity has been associated with metabolic dysfunction, like insulin resistance and body fat mass in both animal and human studies." (PMID 32386512, 2020). "The actions of the enzymes 11βHSD1 and SCD in adipose tissue have both been linked to insulin resistance." (PMID 22721353, 2012). "Elevated levels of SCD activity and desaturation index appear to be associated with key aspects of the metabolic syndrome – insulin resistance, abdominal adiposity and hyperlipidemia – and have been proposed as biological markers for this condition." (PMID 22046234, 2011). "Our findings suggest that these FAs may modulate PPARγ activity through mechanisms involving stearoyl‐CoA desaturase 1 (SCD1), an enzyme implicated in lipid metabolism and insulin resistance." (PMID 40968591, 2025). "Notably, stearoyl-CoA desaturase has been implicated in insulin resistance (IR) together with TCF7L250,51." (PMID 34230558, 2021). "Interestingly SCD-1 is associated with insulin resistance and adiposity, and mouse experiments have shown that disrupting SCD-1 function can potentially reduce body adiposity and improve insulin sensitivity." (PMID 33173055, 2020). "Moreover, a high SCD-1 activity has been also associated with the metabolic syndrome, as well as with an increased risk to develop insulin resistance, cardiovascular diseases and death." (PMID 26511930, 2015). "Studies by Sampat and Lelliott suggested that high SCD activity may be associated with increased lipogenesis and influence ectopic fat deposition and thereby insulin resistance via lipotoxic mechanisms." (PMID 23383292, 2013). "Mice with the SCD gene exhibited reduced diet-induced weight gain and improved insulin resistance compared to wild-type controls." (PMID 33663541, 2021). "In rodents, blocking the expression of stearoyl-coenzyme A desaturase 1 gene (SCD), a rate-limiting enzyme for synthesis of 16:1n7 from 16:0, protected against insulin resistance." (PMID 32530938, 2020). "The fatty acid-modifying enzymes for which connections to insulin resistance and type 2 diabetes have been shown include D5 desaturase, D6 desaturase and SCD." (PMID 27973621, 2016). "The fatty acid-modifying enzymes for which connections to insulin resistance and T2D have been shown include delta-5, delta-6 and delta-9 desaturases (SCD-1) and elongase EloVL6." (PMID 26011768, 2015). "The increases of PGC-1 and SCD-1 are consistent with an insulin resistant phenotype in the liver and correlate with the more severe insulin resistance observed in CD1d−/− mice following HFD feeding." (PMID 24465369, 2014). "We evaluated the modulation of liver stearoyl-CoA desaturase-1 (Scd1) by dietary factors and insulin resistance (IR) in two experimental models of high-fat diet (HFD)-induced nonalcoholic fatty liver disease (NAFLD)." (PMID 24098813, 2013). "Mice fed high fat western diet for one week demonstrate a robust increase in the expression of intestinal SREBF1 and SCD-1, and develop insulin resistance with little change in hepatic gene expression." (PMID 22073239, 2011). "In addition, SCD can affect lipid metabolism and mediate steroidogenesis, playing an important role in insulin resistance." (PMID 37293508, 2023). "We propose that, over time, in the course of type 2 diabetes progression, SCD expression by beta cells is first induced during compensation in response to insulin resistance, and as the duration of diabetes increases, SCD expression decreases leading to a decline in beta cell function." (PMID 31796987, 2020). "Considering these complex relationships and the controversial role of SCD-1 and oleic acid in health and insulin resistance, we hypothesized that adverse maternal conditions in GD may stimulate maternal and fetal SCD-1 activity and thus influence neonatal growth." (PMID 40167637, 2025).
Insulin resistance (continued). "MUFA, which are the products of SCD catalysed reactions, are used as substrates for the synthesis of phospholipids, triglycerides, and cholesterol esters, and thus may increase the lipid burden on tissues and can initiate insulin resistance in patients." (PMID 32303226, 2020). "Similarly, high levels of POA in insulin resistance could be explained by increased activity of SCD." (PMID 30400149, 2018). "These compounds alleviated lipid accumulation and insulin resistance in HepG2 cells through the elevation in PI3K expression and the phosphorylations of Akt and AMPK, and reduction in the expressions of DGAT1 and SCD." (PMID 31340583, 2019). "In the cohort presented here, liver expression levels from statin-regulated lipogenic genes such as ELOVL6, SCD and FASN, which are under transcriptional control by SREBP1, were positively correlated with insulin resistance and the diabetic status." (PMID 31159817, 2019). "The increase of SCD gene promoter methylation levels was related to a decrease in FFA levels and in the insulin resistance index after RYGB." (PMID 28393901, 2017). "Similar mis-regulation of an ACAD and one SCD (CG9743, the ortholog of GI24323) was also reported in flies with insulin resistance in Drosophila melanogaster." (PMID 28832647, 2017). "Therefore, the allopurinol-mediated downregulation of SREBP-1c and SCD-1 genes and the upregulation of PPARα and CPT-1 in the HFD-fed OLETF rats indicate that allopurinol has a beneficial effect on hepatic steatosis in insulin resistance." (PMID 38474414, 2024). "In mice lacking SCD, fatty acid synthesis is decreased and fatty acid oxidation is increased, which protects against hepatic steatosis or insulin resistance." (PMID 35847050, 2022). "As SCD1 inhibition may induce insulin sensitivity in muscle and BAT, it is therefore plausible to explore the use of SCD as a potential therapeutic target for the treatment of insulin resistance and diabetes." (PMID 31554181, 2019).
breast cancer (109 papers, 2009 to 2025). A primary or metastatic malignant neoplasm involving the breast. "With breast cancer patients, the high expression level of SCD-1 is associated with significantly shorter recurrence free survival." (PMID 39920872, 2025). "For example, SCD shows particularly high expression in HER2+ breast cancer and is closely associated with poor prognosis, while NDRG1 is highly expressed in aggressive breast cancer, where it acts as an oncogene promoting tumor growth and metastasis." (PMID 40923764, 2025). "It was reported that high SCD-1 expression is associated with shorter survival in breast cancer patients." (PMID 37151873, 2023). "In some epidemiological studies, the ratio of MUFA to SFA has been used to reflect stearoyl-CoA desaturase (SCD) activity as a predictive marker of breast cancer risk." (PMID 34439311, 2021). "A reduction in ACSL3, FASN and SCD mRNA expression has been observed across the different breast cancer cell lines and linked with fatty acid metabolism-associated genes." (PMID 34944852, 2021). "The enzyme Stearoyl-CoA Desaturase-1 (SCD1), which converts long chain saturated fatty acids to unsaturated fatty acids, has been established as a hallmark of CSCs in many cancers, including breast cancer." (PMID 33266219, 2020). "Epidemiological studies have indeed shown a positive correlation between high levels of SCD-1 expression and the risk of breast cancer as well as adiposity." (PMID 29271901, 2017). "Accordingly, SCD-1 expression is enhanced in breast and prostate cancer tissues in situ compared to normal tissue and SCD-1 expression was associated with shorter survival times in breast cancer patients." (PMID 26022099, 2015). "Expression of SCD is enhanced in human breast cancer tissue and associated with high disease grade." (PMID 27042297, 2016). "MUFAs accumulation in cancer cells was shown to be implicated in carcinogenesis in animal models, but on the other hand, a lower SCD-1 expression/activity may reduce risk of breast cancer." (PMID 25605240, 2015). "This study also clarifies the apparent paradox where estrogen is a known repressor of SCD-1 expression in metabolic tissues, while being an activator of cell proliferation in breast carcinoma cells, a function typically associated with enhanced metabolic activity." (PMID 26022099, 2015). "SCD is a lipid-modifying enzyme that is upregulated in various cancers, including ovarian cancer, breast cancer, gastric cancer (GC), and HCC." (PMID 40084144, 2025). "The activated HER2/PI3K/AKT/mTOR signaling pathway positively correlated with SCD-1 and CD36 expression in PTEN-loss breast cancer cells." (PMID 39920872, 2025). "The interplay between ACSL4, FASN, and SCD underscores a coordinated lipid metabolism axis in BQ-driven breast cancer, with ACSL4 as the key effector of energy production, potentially supporting metastatic potential by providing energy for EMT and invasion." (PMID 40507798, 2025). "Studies revealed that SCD was overexpressed in tumors in prostate, liver, and kidney cancer, and it also correlates with shorter survival in breast cancer." (PMID 40814339, 2025). "This analysis revealed that SCD expression is indeed lower in metastasis and circulating tumour cells from breast cancer patients, compared to the primary tumours." (PMID 39433871, 2024). "The protein expression level of SCD in colorectal cancer, breast cancer, prostate cancer was higher than those in the adjacent normal tissues." (PMID 39351232, 2024). "Stearoyl-CoA desaturase-1 (SCD1) in breast cancer cells can synergistically protect tumor cells with fatty acid binding protein-4 (FABP4) in the tumor microenvironment, shielding them from oxidative stress-induced ferroptosis." (PMID 39664391, 2024). "Stearoyl-CoA desaturase-1 (SCD1) is upregulated in recurrent human breast cancer samples, indicating a poor prognosis for cancer patients." (PMID 39867656, 2024).
breast cancer (continued). "The MCF7 cell line originates from human breast cancer and has high expression of SCD-1, whereas LNCaP originates from a metastatic human prostate cancer that has previously been shown to exhibit non-canonical pathways of desaturation and elongation." (PMID 37402773, 2023). "The lipogenic enzyme, stearoyl-CoA desaturase-1 (SCD1), has been considered a potential target for breast cancer treatment." (PMID 35642041, 2022). "Overall survival analyses suggested that high expression levels of stearoyl-CoA desaturase-1 (SCD1) and PLD2 in breast cancer patients were both associated with metastasis-related morbid outcomes." (PMID 33832505, 2021). "Oleic acid restores the migration of SCD-inhibited breast cancer cell and it is a PTEM/AKT-dependent process in colorectal cancer." (PMID 34503180, 2021). "A notable observation is the upregulation of the microRNA let-7a in LINE-1 silenced T47D cells and the downregulation of SCD in Efavirenz-treated breast cancer cells." (PMID 34944852, 2021). "Lingrand and coworkers recently showed that high expression levels of stearoyl-CoA desaturase-1 (SCD1) promoted the migration of MDA-MB-231 breast cancer cells via the formation of oleic acid and the subsequent induction of PLD-mTOR-S6K signaling." (PMID 33832505, 2021). "Here, we further explored the mechanisms involved in the SCD1-based modulation of breast cancer cell migration and investigated the role of the other human SCD isoform, SCD5." (PMID 29849946, 2018). "Pharmacologic inhibition of SCD activity reduced cell proliferation in human breast cancer cells MCF-7 and MDA-MB-231." (PMID 28412757, 2017). "A similar reduction on spheroid size was observed in MDA-MB-468 breast cancer cells following inhibition of SCD activity." (PMID 27042297, 2016). "Increased expression of SCD has been found in several cancer types, including prostate, liver, kidney and breast cancer." (PMID 27042297, 2016). "We also found that SCD mRNA and protein expression is elevated in human breast cancers and predicts poor survival in high-grade tumours." (PMID 27042297, 2016). "In contrast, only weak SCD staining was detected in invasive lobular carcinomas (ILCs), the second most common breast cancer subtype." (PMID 27042297, 2016). "To confirm the expression of SCD protein in breast cancer, we performed immunohistochemical staining of a breast cancer tissue microarray containing a total of 192 cores representing different breast cancer subtypes." (PMID 27042297, 2016). "The same study also found reduced viability after SCD silencing in breast cancer cells, confirming the importance of this enzyme for cancer metabolism." (PMID 27042297, 2016). "In breast cancer, high levels of SCD expression were confined to invasive ductal breast carcinomas but absent in invasive lobular carcinomas, providing important subtype specification." (PMID 27042297, 2016). "Increased expression of SCD in IDCs compared to other breast cancer subtypes was also confirmed in a published mRNA dataset representing the six most common breast cancer subtypes." (PMID 27042297, 2016). "Although both estrogen and SCD-1 are required for ER + ve breast cancer proliferation, paradoxically it is well documented that estrogen effectively represses SCD-1 expression in liver and adipose tissue possibly through down regulation of SREBP-1c expression." (PMID 26022099, 2015). "This study illustrates for the first time that, in contrast to hepatic and adipose tissue, estrogen induces SCD-1 expression and activity in breast carcinoma cells." (PMID 26022099, 2015). "Although estrogen is required for the proliferation of many estrogen-sensitive breast carcinoma cells, it is also a repressor of SCD-1 expression in liver and adipose." (PMID 26022099, 2015).